IFNAR1 (interferon alpha and beta receptor subunit 1)
Diseases named in the same sentence as IFNAR1 in open-access papers (continued):
Sharing a sentence is not in itself a finding about the gene and the disease.
tumor (218 papers, 2007 to 2026). "Functionally, our study shows that loss of STAT2 suppressed tumor cell proliferation and impaired tumor growth in vivo, whereas loss of IFNAR1 produced the opposite effect, resulting in enhanced tumor growth." (PMID 41440237, 2025). "To assess the impact of STAT2 and IFNAR1 loss on tumorigenicity, we implanted each cell line subcutaneously into immunodeficient Rag1 KO mice and monitored tumor growth over time." (PMID 41440237, 2025). "We have previously demonstrated that reserpine was able to suppress the loss of IFNAR1 in peripheral blood leukocytes in tumor-bearing mice." (PMID 38405101, 2024). "In this study, we performed RNA sequencing and utilized IFNAR1 deficient mice to demonstrate the dependency of Mn‐N/C‐mediated anti‐tumor immune response on the activation of type I IFN signaling." (PMID 38308189, 2024). "Analysis of CD45+ peripheral blood leukocytes (PBLs) isolated from EO771 and 4T1-GFP tumor-bearing mice with tumors of similar size demonstrated that reserpine treatment prevented loss of IFNAR1." (PMID 38405101, 2024). "Reserpine alone and in combination with paclitaxel delayed TNBC tumor growth, decreased TEVs in circulation, and prevented loss of IFNAR1 in CD45+ cells in TNBC tumor-bearing mice." (PMID 38405101, 2024). "By analyzing tumor-infiltrating DCs grown in WT or Ifnar1-KO mice, we demonstrated that IFNAR deficiency completely abolished IR induction of YTHDF1 expression observed in tumors of WT animals." (PMID 39325547, 2024). "Though both diminished and hyperactive IFN1 signaling promoted TNBC metastasis, suppression of EV release using reserpine delayed tumor growth and prevented loss of IFNAR1 in stromal cells even in the presence of paclitaxel." (PMID 38405101, 2024). "As shown for other tumor entities, IFNAR1 deficiency is a well-documented driver of pro-tumoral differentiation of neutrophils, as well as neutrophil migration to organs of metastasis, even prior to metastasis formation." (PMID 35833131, 2022). "Inhibitor of p38 kinase LY2228820 (Ralimetinib) abrogated those effects confirming the role of p38 in ubiquitination and degradation of IFNAR1 caused by tumor-derived factors and ER stress in myeloid cells." (PMID 33741967, 2021). "Both epithelial cell hyper-proliferation and increased tumor burden were associated with the IFNAR1-deficient intestinal epithelium in a colitis-associated cancer model." (PMID 34249014, 2021). "Downregulation of IFNAR1 (one of the chains in the receptor complex) lets tumor elude the IFN pathway which causes cancer development." (PMID 34858438, 2021). "The authors further demonstrate that the improved response was due to reduced type I IFN-mediated induction of a granzyme inhibitor, Serpinb9, thus making IFNAR1-deficient tumor cells more sensitive to CD8+ T cell killing." (PMID 33238631, 2020). "We next used a VSV-GP variant expressing firefly luciferase (VSV-GP-Luc) to monitor intratumoural virus activity depending on tumour permissiveness (IFNAR1 wt or deficient) and adaptive immune status (syngeneic C57BL/6J mice vs. athymic nude mice)." (PMID 31530903, 2019). "This poses cancer risk as evidenced by Ifnar1-expressing mice displaying decreased GI tumor burden corresponding with decreased mucosal inflammation." (PMID 28428788, 2017). "Restoration of IFNAR1 expression in the T cells was associated with renewed control over tumor growth." (PMID 29050360, 2017). "The upregulation of IFNAR1/2 associated with the BRAFV600E mutation might be linked to the enhanced susceptibility of tumor cells to PDT, potentially rendering BRAFV600E-mutated cells more responsive to stimuli that activate the IFN-1 pathway." (PMID 39061208, 2024). "Furthermore, both depletion of CD8+ T cells and IFNAR1 blockade abolished the growth retardation of TRIM21-deficient tumours after radiation treatment." (PMID 36797289, 2023).
tumor (continued). "Previously, we could already show for different tumor entities that the deficiency in type I IFN signaling leads to the elevated tumor growth in Ifnar1-/- mice and changed tumorigenic properties of tumor-associated neutrophils." (PMID 35833131, 2022). "Finally, to prove the therapeutical effect of IFN-λ on anti-tumor immune responses and tumor growth in IFNAR1-deficient animals in vivo, we set tumors into mice and treated animals with IFN-λ as described in methods." (PMID 35833131, 2022). "This in turn could be responsible for the observed accelerated tumor growth in IFNAR1-deficient mice." (PMID 35833131, 2022). "Interestingly, we found MDSC with reduced suppressive function in Ifnar1-deficient hosts; however, there was a common flaw in immune cell activation, which was reflected by defective immune cell activation and tumor control." (PMID 31694706, 2019). "Using IFN receptor 1 (IFNAR1)-deficient mice, we show that IFNAR signaling may play an important role during MDSC development in tumor-bearing hosts, promoting a suppressive phenotype." (PMID 31694706, 2019). "Using mouse models for tumor transplantation and primary development, it was shown that non-immune-edited (immunogenic) sarcomas grown in rag2-deficient mice (which lack lymphocytes) were rejected by wild-type syngeneic mice; however IFNAR1 blockade abrogated this effect." (PMID 34925363, 2021). "To assess the functional impact of Stat2 and Ifnar1 deletion on tumor cell growth, we evaluated their proliferative capacity in vitro and in vivo." (PMID 41440237, 2025). "Analysis of basal protein levels revealed that total expression of STAT1, STAT2, and STAT3 remained largely unaffected in both STAT2 KO and IFNAR1 KO tumor cells, indicating that deletion of either gene does not alter steady-state STAT2 protein abundance." (PMID 41440237, 2025). "We observed that G0S2 knockout alone was sufficient to suppress tumor growth in mice, whereas administration of the IFNAR1 inhibitor in the control group promoted tumor growth." (PMID 40519301, 2025). "To assess the functional relevance of type I IFN signaling in this TME, we treated tumor-bearing Prf1–/– mice with a neutralizing antibody against IFNAR1, a subunit of type I IFN receptor." (PMID 40627458, 2025). "One unexpected finding was that zebularine-induced antigen processing and presentation(MHC-AgPP) was abolished in tumor-bearing IFNAR1-/- mice." (PMID 38755254, 2024). "The deletion of IFNAR1 in mouse cancer cells led to an enhanced anti-tumor response after ionizing radiation, mediated by CD8+ T cells." (PMID 38672681, 2024). "This pathway involved predominantly CD8+ T cells, and, to a lesser extent, CD4+ T cells, but no other lymphoid or myeloid populations, was restricted to the tumor microenvironment and required IFNAR1 recognition." (PMID 39213189, 2024). "Consistently, the induced tumor‐infiltrating CD8+ T cells by the combination treatment group relative to the CTRL group were mitigated by IFNAR1 or CD8 neutralization or STING knockout." (PMID 39412086, 2024). "In tumor-associated macrophages (TAM), autocrine type I IFN signaling sustains a proinflammatory M1-like phenotype and downregulation of IFNAR1 has been shown to promote immune-suppressive activity in tumor-infiltrating myeloid cells." (PMID 39056192, 2024). "Several studies, using either IFNAR1 knockout mice or anti-IFNAR1 blocking antibodies have highlighted the pivotal role of this signaling pathway, specifically in the priming of adaptive anti-tumor responses." (PMID 38318190, 2024). "We further determined the CD8+T cell immune response in MC38 tumor‐bearing WT and Ifnar1−/− mice after Mn‐N/C administration." (PMID 38308189, 2024). "Depletion of cGAS, STING, IRF3, or IFNα/β receptor 1 (IFNAR1) abolishes this increase, indicating that 5-FU/oxaliplatin mediated upregulation of PD-L1 expression is dependent on tumor cell intrinsic cGAS/STING signaling." (PMID 39469633, 2024).
tumor (continued). "The administration of anti‐IFNAR‐1 antibody effectively inhibited the PS‐mediated anti‐tumor response." (PMID 38900071, 2024). "Tumor-derived IFN favors the expression of PDL1 in tumor cells via IFNAR1/STAT1 and PD1 in immune cells, resulting in immune suppression in head and neck malignancies (HNSCCs)." (PMID 38672681, 2024). "IFNAR1 regulation affects the function of fibroblasts, and change matrix formation in the tumor microenvironment, thereby promoting tumor growth." (PMID 39867908, 2024). "We first treated naive mice with r3LCMV, and after 3 weeks, we treated these mice with control antibodies or IFNAR1-blocking antibodies, followed by B16 tumor challenge." (PMID 38861331, 2024). "In IFNAR1-/- mice tumor models, we found that IFNAR1 depletion abrogated the anti-tumor effect of zebularine." (PMID 38755254, 2024). "Further, we added the supernatant from Ogt+/+ or Ogt−/− B16-OVA tumor cells into the co-culture system of Ifnar1 knockout BMDCs and OT-I cells." (PMID 38168435, 2024). "We observed a significant increase in the frequency of PD1+CD8+ T cells in tumors of mice bearing the Arf1‐ablated tumor cells, whereas the increase was completely abolished after treatment with both anti‐IFNAR1 and anti‐IL‐1β antibodies." (PMID 37786300, 2023). "SMA-560 showed no phenotype, whereas the GL-261 model showed increased survival of mice when IFNAR1 signaling in the tumor was abrogated." (PMID 36571986, 2023). "DMBA3-4 tumor rejection persisted in Ifng–/– (IfngKO); Klrk1–/– (Klrk1KO); Sting–/– (StingKO); Ifnar1–/– (Ifnar1KO); Ticam1–/–,Myd88–/– (Ticam1KO Myd88KO); and Ncr1iCre,ROSADTR mice." (PMID 37843274, 2023). "Stabilizing IFNAR1 using p38 inhibitor combined with IFN induction therapy elicits a robust anti-tumor effect via undermining suppressive activity of MDSCs in tumor bearing mice." (PMID 37006306, 2023). "ASO-VPS significantly reduced the tumor volumes and reduced Ifnar1 expression in murine tumors compared to ASO-NC treatment." (PMID 36458816, 2022). "When the tumor was allowed to grow until day 42, anti-IFNAR1 antibody treatment significantly abrogated the tumor growth control effect observed with the unmodified OVA-LNP in the isotype control group." (PMID 36311701, 2022). "We found that the expression of IFNAR1 in ccRCC tissues was significantly lower than that in para-tumor tissues." (PMID 36612165, 2022). "Our results show that the on/fast-off dynamics of IFNβ signalling are crucial to the response to ICB, which can be therapeutically exploited using antibodies against IFNβ or its receptor IFNAR1, resulting in enhanced tumour clearing." (PMID 35986006, 2022). "As mechanism of action, miR130b downregulated tumor OX40L expression by directly targeting IFNAR1/p-STAT1 axis, recruiting Th17 cells via OX40/OX40L interaction, thereby promoting immunosuppressive function of Th17 cells." (PMID 35301282, 2022). "In light of strongly elevated primary tumor growth in Ifnar1-/- mice this phenomenon suggests pro-tumoral bias of such LN neutrophils." (PMID 35833131, 2022). "The immune-privileged tumour microenvironment induced by IFNAR1 inactivation can be partly explained by interference of immune cell homeostasis." (PMID 36104718, 2022). "VPS9D1-AS1 knockout downregulated OAS1, an ISG gene, which further reduced IFNAR1 levels in tumor cells." (PMID 36458816, 2022). "To further assess the mechanism of anti-tumor immunity, we measured WT, Gcc2KO and Rab14KO B16 tumor growth in either Rag1−/− or Ifnar1−/− mice." (PMID 36379959, 2022). "To further delineate the upstream pathway essential for IFNAR1 upregulation in tumor cells, we applied the CRISPR/Cas9 technique to abolish OAS1 expression." (PMID 36458816, 2022). "To further illuminate the mechanism of neutrophil recruitment, we performed analyses of CCR7 expression on LN neutrophils and observed significant upregulation of this receptor on Ifnar1-/- cells in tumor-bearing animals as compared to tumor-free mice." (PMID 35833131, 2022).
tumor (continued). "Collectively, these data suggest that inactive IFNAR1 on neutrophils leads to the prominent defect in the neutrophil-mediated activation of anti-tumor T-cell responses in TDLNs." (PMID 35833131, 2022). "First, we evaluated the growth of transplantable MOPC in WT and type I IFN receptor (IFNAR1) knockout (Ifnar1-/-) mice and observed significantly elevated primary tumor growth in Ifnar1-/- animals compared to WT controls." (PMID 35833131, 2022). "Remarkably, the major tumor regression seen by day 12 in the CPA + control IgG mouse group was fully blocked in all 16 mice given CPA + anti-IFNAR1 antibody." (PMID 36187936, 2022). "As one of the subunits constituting the type 1 interferon receptor, IFNAR1 has been confirmed to play a key role in the anti-tumor immunity of IFN-1." (PMID 36612165, 2022). "To this end, we treated Ifnar1-/- tumor-bearing mice with IFN-λ and monitored neutrophil/T-cell interactions using the in vivo multiphoton imaging." (PMID 35833131, 2022). "Mice receiving anti-IFNAR1 antibody showed a significant increase in PD-1 expressing tumor-infiltrated CD4+ and CD8+ T cells and a significant increase in tumor-infiltrating M2-like macrophages (CD206+ F4/80+), compared to the isotype control treated group." (PMID 36311701, 2022). "We then carried out an additional experiment by treating tumor-bearing mice with IFNAR1 or CD8 blocking antibodies." (PMID 35641483, 2022). "At the same time, the apoptosis-related gene PIM1, proliferation-related gene CCND1, migration- and invasion-related gene BMPR2, and tumor immunocyte infiltration-related gene IFNAR1 also appeared in the core network." (PMID 35241097, 2022). "We have evaluated spatiotemporal patterns of neutrophil/T-cell interactions in LNs in the context of type I interferon receptor (IFNAR1) availability in tumor-free and tumor-bearing animals." (PMID 35833131, 2022). "The ability of anti-IFNAR1 antibody to almost completely abolish CPA-induced E0771 tumor regression establishes that type I IFN signaling is essential for the anti-tumor actions of metronomic CPA in this model." (PMID 36187936, 2022). "In transplantable models, spleen PMN-MDSC demonstrated markedly lower expression of IFNAR1 than corresponding PMN from tumor-free mice." (PMID 33741967, 2021). "For example, activation of IFN-I signaling was shown to be correlated with abscopal effects of the combination therapy of anti-CTLA-4 and RT, which were abrogated when IFNAR1 was knocked down in tumor cells." (PMID 34830176, 2021). "IFNAR1 expression in tumor PMN-MDSC was substantially lower than in spleen PMN-MDSC, whereas only in CT26 TB mice it was lower in M-MDSC." (PMID 33741967, 2021). "The cell line used for tumor implants in these studies was B16‐F10, isogenic to the Bl6 background of this Ifnar1‐strain." (PMID 34762341, 2021). "We tested the effect of THG and tumor cell-conditioned medium on ubiquitination and degradation of IFNAR1 in THP-1 myeloid cell line." (PMID 33741967, 2021). "We observed dramatically reduced expression of IFNAR1 on the surface of tumor PMN-MDSC and M-MDSC than on spleen cells." (PMID 33741967, 2021). "Multiple immunofluorescence staining showed that TRAIL+ T cells expressed IFNAR1 in in situ tumor sections from patients with CRC." (PMID 33414378, 2021). "TES from different primary human tumors, as well as supernatant from tumor cell line PCI-30, caused substantial decreases in IFNAR1 expression." (PMID 33741967, 2021). "Whereas deletion of IFNAR1 is not sufficient to convert neutrophils and monocytes to MDSC, genetic stabilization of IFNAR1 in tumor bearing mice undermines suppressive activity of MDSC and has potent antitumor effect." (PMID 33741967, 2021). "Given the difference in IFNAR1 levels in tumor and spleen MDSCs, we next compared side-by-side functional activities of MDSC in tumors and spleens." (PMID 33741967, 2021).
tumor (continued). "Stabilizing IFNAR1 using inhibitor of p38 combined with the interferon induction therapy elicits a robust anti-tumor effect." (PMID 33741967, 2021). "In a recent study using a preclinical model of triple negative breast cancer, specific deletion of Ifnar1 expression in NK cells demonstrated a requirement for IFNI in NK cell-mediated tumor cell lysis." (PMID 33801234, 2021). "The therapeutic efficacy of PD-1 mAb on tumor growth was almost completely abolished by co-administration of neutralizing Abs against IFNAR1 and TNFR." (PMID 33414378, 2021). "Both, THG and tumor cell-conditioned medium triggered phosphorylation and ubiquitination of IFNAR1 while decreasing total levels of IFNAR1 protein." (PMID 33741967, 2021). "Further, a consensus on the role of tumor expression of IFNAR1 and IFNGR1 regarding RT response still cannot be reached, as either an essential role or a dispensable role was reported." (PMID 34830176, 2021). "In line with previous reports, PDL1 upregulation by MAFO was dependent on IFNAR and TLR-3 signaling as it was abrogated in tumor cells where IFNAR1 was blocked by neutralizing Ab or in MCA-Tlr3-/-." (PMID 32290265, 2020). "Based on these findings, we further demonstrated enhanced tumor control and overall survival in mice treated with IFNAR1 KO CAR T cells in combination with VSVmIFNβ." (PMID 32581235, 2020). "The anti-tumour effects of the TLR3 agonists were also abolished in IFNAR1 knockout mice, highlighting a key role for type I IFN signalling." (PMID 33352882, 2020). "In plasma of tumor-bearing type I IFN receptor knockout (Ifnar1-/-)mice increased Gcsf levels and higher neutrophil counts were observed, as compared to WT animals." (PMID 31717318, 2019). "Consistently with these observations, in vivo IFNAR1 blockade restored a tumor-promoting immune response and broke dormancy of MR20 cells." (PMID 30546090, 2019). "Tumours with high expression of IFNAR1 had few cytotoxic T lymphocytes (CTLs, CD8 + cells) and CD56+ NK infiltration, and vice versa." (PMID 30555157, 2019). "Meanwhile, IFNAR1 expression was also higher in tumour tissues than that in adjacent normal tissues in the 22 HNSCC patients from the GEO database." (PMID 30555157, 2019). "Taken together, the IFNAR1 signaling pathways comes into play in tumor cells and leukocytes to subvert tumor growth control by anti-PD-1 mAb, especially when type I IFNs are produced by both CD45+ and CD45− cellular compartments." (PMID 31481761, 2019). "We next investigated the role of IFNAR1 expressed by the host or intrinsically by tumor cells in affecting the sensitivity of MCA205WT tumors to anti-PD-1 mAb in vivo." (PMID 31481761, 2019). "Following IR, Serpinb9-KO B16F10 tumors had a prolonged tumor growth delay equivalent to that of irradiated Ifnar1-KO B16F10 tumors." (PMID 31483286, 2019). "Tumor control benefits were consistently observed, however, in Ifnar1-KO tumors with the addition of anti–PD-L1 treatment." (PMID 31483286, 2019). "In summary, we demonstrate that endogenous IFNα promotes the expression of PDL1 through IFNAR1/Stat1 in tumour cells and PD1 in immune cells, which contributes to immunosuppression formation in HNSCCs." (PMID 30555157, 2019). "Secondary IFNAR1 transcripts have been reported in tumor cell lines and here, for the first time, we report that −77VNTR genotype is crucial for their production, which apparently leads to the transcriptional remodeling of IFNAR1 gene." (PMID 29713327, 2018). "The expression of IFNAR1 was correlated with that of IRF1 in the tumor tissue of adenocarcinoma and those of IRF1 and IRF7 in the normal tissue of SCC." (PMID 30305853, 2018). "The protein levels of ATF4 and PDL1 had the closest proximity in both tissues, and they formed a cluster with those of IRF1, eIF2α, and IFNAR1 in the tumor tissue." (PMID 30305853, 2018). "Knockdown of IFN-β receptor (IFN-α receptor 1) in B6/IFNAR1 KO mice abolished RT's ability to reduce tumor growth in this model." (PMID 30766539, 2018).